ACE (angiotensin I converting enzyme)
Diseases named in the same sentence as ACE in open-access papers (continued):
Sharing a sentence is not in itself a finding about the gene and the disease.
atherosclerosis (continued). "Among the hypotensive agents, blocking the effects of angiotensin II (Ang II) via angiotensin-converting enzyme (ACE) inhibitors or Ang II type 1 (AT1) receptor antagonists has in most studies resulted in decreased atherosclerosis." (PMID 25785279, 2015). "Further, it was shown that other drugs that are most frequently used in the secondary prevention of atherosclerosis, like statins and ACE inhibitors, have in patients with PAD hemodynamic effects, improving the claudication distance and quality of life." (PMID 26121301, 2015). "Transcriptional screening of ACE-overexpressing monocytes revealed noticeably increased expression of Angiotensin II receptors and adhesion- as well as atherosclerosis-related ICAM-1 and VCAM1." (PMID 25003524, 2014). "Together these findings are compatible with the notion that vitamin E treatment and ACE inhibitor treatment protected the aortic intima of atherosclerosis-prone ApoE−/− mice against ROS-mediated damage." (PMID 23801967, 2013). "Our findings complement those studies by showing that vitamin E treatment and ACE inhibition mediated similar effects concerning the protection of the aortic intima and media in atherosclerosis-prone ApoE−/− mice." (PMID 23801967, 2013). "To identify atherosclerosis-related pathomechanisms with concordant sensitivity to vitamin E treatment and ACE inhibition, we performed whole genome microarray gene expression profiling of aortic genes." (PMID 23801967, 2013). "In this study, we investigated the association between the ACE c.2306-117_404 I/D, AGTR1 c.1080*86A>C and CYP11B2 c.-344C>T polymorphisms, within the genes encoding for RAAS proteins, and the extent of atherosclerosis." (PMID 22307319, 2012). "The enhanced ACE expression in macrophages and smooth muscle cells of coronary artery plaques has been previously reported to indicate that ACE activity in lesions contributes greatly to the progression of atherosclerosis." (PMID 22307319, 2012). "For atherosclerosis, pharmacological inhibition of AngII synthesis, through inhibition of ACE or renin, reduced the size of atherosclerotic lesions in several experimental models of atherosclerosis." (PMID 23236507, 2012). "At an early stage of atherosclerosis, the treatment with different ACE inhibitors reduced endothelial dysfunction in atherogenic diet-fed or hyperlipidemic rabbits." (PMID 19390623, 2009). "The anti-inflammatory effects of statins and the effect of angiotensin-converting enzyme (ACE) inhibitors on endothelial dysfunction are well established in atherosclerosis." (PMID 17497040, 2007). "ACE has been shown to play an important role in development of atherosclerosis, presumably via its proinflammatory effects." (PMID 16722611, 2006). "Consequently, ACE inhibition decreases arterial NF-κB activation in macrophages and vascular smooth muscle cells, which are pivotal in the pathophysiology of atherosclerosis." (PMID 40520007, 2025). "ACE inhibitors, like statins, have proven useful in treating atherosclerosis." (PMID 40870420, 2025). "It was found that administration of VPP and IPP might be beneficial for preventing atherosclerosis due to the activity of ACE and hypercholesterolemia." (PMID 38672494, 2024). "Adding the causal genes ACE, AGT, AGTR1, and REN to list 2+ (n = 9+4) revealed AOC3 with at least one causal gene to be associated with Transition Metal Ion Binding (GO:0046914, q = 2.288x10-2), and Atherosclerosis (q = 2.821x10-5)." (PMID 39480826, 2024). "What was observed in several previous studies is that ACE 10/10 mice have a highly effective immune response to a variety of immune challenges, including tumors, infection, and models of chronic diseases such as atherosclerosis and Alzheimer’s disease." (PMID 38746124, 2024). "Taken together, ACE overexpression modifies the character of monocytes which is subsequently reflected in the enhanced metabolic function and reparative-polarized status of differentiated macrophages in atherosclerosis." (PMID 37928535, 2023).
atherosclerosis (continued). "Moreover, the increased ACE expression in macrophages infiltrating atherosclerotic plaques can serve as a marker to evaluate the severity of atherosclerosis." (PMID 37928535, 2023). "Thus, myeloid lineage-specific ACE overexpression alters the populational balance of peripheral blood circulating monocytes in atherosclerosis." (PMID 37928535, 2023). "Moreover, overexpression of ACE in myeloid cells enhances the immune response against tumors, infections, Alzheimer's disease, and atherosclerosis in mice models." (PMID 35836993, 2022). "Because BDKRB2 enhanced the endothelial dysfunction of Tg-B2++ApoE–/– mice, we asked whether inhibition of ACE-dependent angiotensin II generation in Tg-B2++ApoE–/– mice could retard the BDKRB2-enhanced atherosclerosis progression." (PMID 30847343, 2019). "The researchers found no relation between ACE I/D polymorphism and atherosclerosis and also between types of genotype, ACE activity, and OxLDL level." (PMID 31370787, 2019). "Despite the small sample size, this investigation showed the study of ACE I/D polymorphism did not proper for the prediction of atherosclerosis." (PMID 31370787, 2019). "Over the last few decades, significant changes occurred in medical therapy of patients with CAD and atherosclerosis in general, due to the marketing of new drugs like statins, ACE-inhibitors/ARB or thienopyridine, and the wider use of old but efficacious drugs like aspirin." (PMID 30035118, 2018). "Subgroup analysis identified intermediate monocytes expressing angiotensin-converting enzyme (ACE) were significantly higher in CKD patients with severe atherosclerosis and may yield additional prognostic value." (PMID 25852821, 2015). "GO analysis of probe sets with significantly lower expression upon treatment compared to untreated ApoE−/− aortas detected that vitamin E and ACE inhibition prevented the up-regulation of muscle-specific genes in the atherosclerosis-prone aorta of ApoE−/− mice." (PMID 23801967, 2013). "In agreement with inhibition of the aortic recruitment of pro-inflammatory T cells by captopril, ACE inhibitor treatment with captopril prevented the atherosclerosis-related increase in the aortic content of the T cell-specific Cd8b protein of ApoE−/− mice as determined by immunoblotting." (PMID 23801967, 2013). "Our study revealed vitamin E-like effects of ACE inhibition regarding prevention of atherosclerosis-induced alterations of the aortic intima and media whereas aortic recruitment of pro-inflammatory immune cells and neurodegeneration of perivascular nerves were not sensitive to vitamin E treatment." (PMID 23801967, 2013). "To investigate the antioxidant effect of angiotensin II inhibition on atherosclerosis, we compared the treatment effect of the ACE inhibitor captopril with that of the antioxidant vitamin E. As disease model of atherosclerosis, we used hypercholesterolemic ApoE−/− mice." (PMID 23801967, 2013). "GO analysis of probe sets with significantly higher expression after treatment compared to untreated ApoE−/− aortas and immunohistology analysis revealed that vitamin E treatment and ACE inhibition prevented the atherosclerosis-related down-regulation of aortic intima genes of ApoE−/− mice." (PMID 23801967, 2013). "Additional vitamin E-insensitive effects targeting atherosclerosis-enhancing aortic immune cell recruitment and perivascular nerve degeneration could account for the stronger anti-atherogenic activity of ACE inhibition compared to vitamin E." (PMID 23801967, 2013). "We may also speculate that in these regions JNK and ACE are more active, since they are excluded from the SS-induced response, favoring atherosclerosis progression." (PMID 21901117, 2011). "ACE inhibitors have beneficial effects on the prognosis and progression of atherosclerosis, suggesting that they may be antioxidant agents that can reduce vascular oxidative stress in cardiovascular events." (PMID 20444272, 2010).
atherosclerosis (continued). "Therefore, further studies are needed to clarify the role of ACE inhibitors and ARBs in atherosclerosis in animal models with high angiotensin II levels." (PMID 19390623, 2009). "In addition, experiments on coronary arterioles obtained from patients suffering from atherosclerosis showed that the incubation of these vessels with an ACE inhibitor (Lisinopril) significantly ameliorated the vasodilatory responses to several endothelium-dependent agonists." (PMID 38279313, 2024). "Thus, it appears that ACE 10/10 macrophage polarization is more exaggerated irrespective of whether disease triggers a dominant proinflammatory M1 response or, as in atherosclerosis, a reparative M2 process." (PMID 38763333, 2024). "However, our recent findings suggest that enhanced ACE expression might support maintaining the metabolic function of macrophages, thus preventing the progression of atherosclerosis." (PMID 37928535, 2023). "However, the importance of ACE in peripheral blood monocytes, which are the primary precursors of lesional-infiltrating macrophages, is still unknown in atherosclerosis." (PMID 37928535, 2023). "Therefore, we do not predict that the presence of AT1aR or ACE on endothelial cells would affect atherosclerosis in PTC-specific AT1aR or ACE deficient mice." (PMID 37655218, 2023). "Hence, our findings suggest that the upregulation of ACE may positively enhance metabolic reactions in macrophages, which ultimately provides a protective effect in atherosclerosis." (PMID 37928535, 2023). "Our study revealed the ACE I/D polymorphism of the ACE gene may not be an independent risk factor in the development of atherosclerosis and evaluation of ACE activity level is more important in evaluating the risk of disease." (PMID 31370787, 2019). "Thus, ACE can affect BP and accelerate the progression of atherosclerosis." (PMID 26710338, 2015). "As reduction in serum ACE activity, even with no decrement in blood pressure BP, was previously shown to attenuate atherosclerosis, PJ can offer a wide protection against cardiovascular diseases which could be related to its inhibitory effect on oxidative stress and on serum ACE activity." (PMID 23908863, 2013). "Moreover, ACE has been shown to inhibit atherosclerosis progression." (PMID 23826288, 2013). "Also, the results of meta-analysis investigating the association between the ACE c.2306-117_404 I/D polymorphism and the carotid artery intima-media thickness (IMT), used to detect the presence and to follow the progression of atherosclerosis, correspond with our work." (PMID 22307319, 2012). "Moreover, angiotensin I-converting enzyme (ACE) inhibitors have been reported to have beneficial effects on the prognosis and progression of atherosclerosis, suggesting that they can be antioxidant agents that can reduce vascular oxidative stress in cardiovascular events." (PMID 20444272, 2010). "In the present review, we focused on angiotensin-convertingenzyme (ACE) inhibitors, angiotensin II receptor blockers (ARBs), and renin inhibitors to update the direct activities of the renin-angiotensin system in inflammatory processes governing atherosclerosis." (PMID 19390623, 2009). "Since bothincreased ET-1 production and decreased NO bioavailability are deeply involvedin the pathophysiology of atherosclerosis, reciprocal changes in ET-1 andNO production by the vascular endothelium could contribute to the benefitsderiving from clinical use of ACE inhibitors." (PMID 19079593, 2008). "Conversely, during the stages of atherosclerosis regression, innate immune cells can express ACE (angiotensin-converting enzyme), IL-4, and IL-10 and TGF-β to attract reparative lymphocytes like Th2 cells." (PMID 38774876, 2024). "There is a highly consistent literature that inhibition of ACE or blockade of AT1R have protective effects on hypercholesterolemia-induced atherosclerosis, although most studies only reported male mice." (PMID 37655218, 2023).
atherosclerosis (continued). "This angiotensin-converting enzyme (ACE) inhibitor canstimulate NO production, decrease the progression of atherosclerosis, and inhibitthe expression adhesion molecules on endothelial cells by reducing reactiveoxygen species." (PMID 39076864, 2023). "Captopril treatment prevents neutrophil activation through a potential ACE-related pathway in LTB4 activation, an inflammatory signal molecule involved in many conditions, such as psoriasis and atherosclerosis." (PMID 36016727, 2022). "Therapies that are commonly used for treatment of atherosclerosis, such as statins, angiotensin receptor AT1 antagonists and angiotensin converting enzyme (ACE) inhibitors, often show pleiotropic antioxidant effects." (PMID 32245238, 2020). "Angiotensin-converting enzyme (ACE)/angiotensin II (Ang II)/angiotensin II type 1 receptor (AT1R) axis is the main pathway of RAS and contributes to the pathogenesis of atherosclerosis." (PMID 29066981, 2017). "Blocking renin-angiotensin system (RAAS) with an inhibitor of angiotensin converting enzyme (ACE) reduced IL-6 and inflammation markers in atherosclerosis experimental model." (PMID 26578976, 2015). "Inhibition of ACE and/or employment of AngII receptor 1 (AT1R) antagonists has been shown to be effective in decreasing clinical events in patients with atherosclerosis." (PMID 25003524, 2014). "The generation of angiotensin II was suppressed by the angiotensin-converting enzyme (ACE) inhibitor captopril, which has a well-established atherosclerosis-inhibitory activity in animal models and patients." (PMID 23801967, 2013). "Angiotensin-converting enzyme (ACE), a key enzyme in the RAS, plays important roles in vascular remodeling, atherosclerosis, and ischemic stroke." (PMID 23049705, 2012). "In a European cohort of CAD patients treated with CABG, the ACE genotype was an independent predictor of total and cardiac mortality in two-year follow up, explaining 17.7% of cardiac events, although a relationship of I/D polymorphism with graft atherosclerosis was not investigated." (PMID 19497121, 2009). "Additionally, they reprogram macrophage metabolism by modulating ACE expression towards oxidative phosphorylation (OXPHOS), aiming to mitigate atherosclerosis." (PMID 38774876, 2024). "Our previous study has demonstrated that deletion of AT1aR or ACE on endothelial cells does not contribute to atherosclerosis." (PMID 37655218, 2023). "The present study provided direct evidence that AT1aR or ACE deletion on PTCs in adult mice does not affect hypercholesterolemia-induced atherosclerosis." (PMID 37655218, 2023). "Second, inducible PTC-specific AT1aR or ACE deletion does not affect systolic blood pressure and atherosclerosis in hypercholesterolemic mice." (PMID 37655218, 2023). "Despite profound deletion of AT1a receptor or ACE in PTCs, the absence of either protein did not influence development of atherosclerosis in either sex." (PMID 37655218, 2023). "RAAS blockade with angiotensin converting enzyme (ACE) inhibitors or angiotensin receptor blockers (ARBs) has been reported as beneficial for disease outcome in AMI patients via preventing/reversing endothelial dysfunction and atherosclerosis." (PMID 36407428, 2022). "Monocytes express elevated levels of angiotensin converting enzyme (ACE) in ESRD patients, which has been hypothesized to contribute to accelerated atherosclerosis." (PMID 32887404, 2020). "The results also indicated that the relationship between genotype interaction and enzyme activity of ACE in increasing the chances of developing atherosclerosis was not significant." (PMID 31370787, 2019).
atherosclerosis (continued). "AGT, ACE, and or AGTR-1 mRNA and protein levels are elevated in arterial cells of type 2 diabetic patients, and RAS inhibition reduces the onset of T2D and prevented atherosclerosis." (PMID 19742300, 2009). "Here, we discuss both classical (angiotensin) and nonclassical functions of ACE and highlight mice called ACE 10/10 in which genetic manipulation increases ACE expression by macrophages and makes these mice much more resistant to models of tumors, infection, atherosclerosis, and Alzheimer’s disease." (PMID 38763333, 2024). "Unfortunately, there are no optimal mouse models available to study whether AT1aR or ACE in the whole kidney contributes to hypercholesterolemia-induced atherosclerosis." (PMID 37655218, 2023). "However, the present study cannot rule out that deletion of AT1aR or ACE in the entire kidney contributes to atherosclerosis." (PMID 37655218, 2023). "However, the atherosclerosis-lowering potential of ACE inhibition does not necessarily rely on bradykinin-stimulated Bdkrb2 activation, e.g., when there is no activation of the (brady)kinin-generating kallikrein system." (PMID 30847343, 2019). "One possible explanation for the greater familial clustering of SBP in users than in non-users of ACE inhibitors could thus be that patients treated with ACE-inhibitors had more atherosclerosis and endothelial dysfunction than non-users of ACE inhibitors." (PMID 16509973, 2006). "Inducible PTC-specific deletion of AT1aR or ACE or increases of human AGT and renin in adult mice does not affect blood pressure and atherosclerosis in hypercholesterolemic mice." (PMID 37655218, 2023).